WEE1 (WEE1 G2 checkpoint kinase)
Diseases named in the same sentence as WEE1 in open-access papers (continued):
Sharing a sentence is not in itself a finding about the gene and the disease.
cancer (continued). "The mechanism by which WEE1 and CDC25 become deregulated during cancer development remains still unclear." (PMID 33585466, 2020). "Because of the important role of Wee1 in the G2/M checkpoint along with CHK1/2, using Wee1 inhibitors such as AZD1775 or MK 1775, can relieve G2 arrest, sensitizing cancer cells to radiotherapy." (PMID 32355263, 2020). "This clearly suggests a key role of Wee1 in HNSCC cells, and involvement of Wee1 in squamous (pre)cancer cell cycle regulation." (PMID 32047167, 2020). "Several in vitro studies on the role of a specific WEE1 inhibitor (WEE1i) adavosertib (AZD1775, MK1775) in combination therapies of several cancer models have been conducted." (PMID 32605254, 2020). "In genomically unstable cancers such as DLBCL, WEE1 is highly expressed and a relevant target for therapy." (PMID 31703356, 2019). "Many of these drugs were developed originally for cancers in adults, but there are ongoing pediatric early phase studies of PARP inhibitors and WEE1 inhibitors, alone or in combination with chemotherapy." (PMID 35582583, 2019). "In contrast, targeting WEE1 or CHEK1 sensitizes cancer cells to DNA-damaging drugs, supporting WEE1 and CHEK1 as potential targets and chemosensitizers for cancer therapy." (PMID 31387297, 2019). "We previously demonstrated high expression of WEE1 in DLBCL cells compared to normal B-cells and found this difference is significantly higher in DLBCL compared to other cancers." (PMID 31703356, 2019). "Previous studies, including our own, have demonstrated synergism between G2/M DNA damage checkpoints inhibitors (WEE1, Chk1 or ATR) and PARPi in several cancer models." (PMID 31191824, 2019). "WEE1 inhibition by AZD1775 induces both premature mitotic entry and DNA damage in various types of cancer cells." (PMID 31703356, 2019). "Treatment with the WEE1 inhibitor significantly reduced the cell viability of 92.1 and OCM1 UVM cells, compared with other cancer cells." (PMID 31848373, 2019). "The DNA damage checkpoint, a pivotal target of WEE1 by CDC2 phosphorylation, stalls the cell cycle and protects cancer cells from death in response to unrepaired DNA lesions." (PMID 29954437, 2018). "In particular, the four overlap non-cancer genes (CDK1, CDK2, PLK1 and WEE1), which were validated by the three data resources, were all known anticancer drug targets and clinical trial targets." (PMID 29855504, 2018). "The key components of the G2/M checkpoint, being CHK 1&2, WEE1 and CDC25, are interesting targets for cancer therapy as the activation of this checkpoint leads to DNA repair." (PMID 29113422, 2017). "Preclinical efficacy of the Wee1 inhibitor AZD1775, also known as MK1775, was assessed in several cancers on the basis of the concept of synthetic lethality." (PMID 28978051, 2017). "Interesting targets to overcome these cancer defense mechanisms are: PARP, DNA-PK, PI3K, ATM, ATR, CHK1/2, and WEE1 inhibitors." (PMID 29113422, 2017). "As such, miR‐15b has been reported to regulate Wee1, Bcl‐2, cyclin E, cyclin D and/or IGF‐1R expression in several types of cancer, and many of these genes also play important roles in drug resistance and apoptosis resistance." (PMID 28145098, 2017). "The second strategy relies on addiction of cancer cells transformed by active oncogenes (such as Ras, Myc or Cyclin E) to ATR, Chk1, and Wee1 kinases that allow them to cope with a high level of replication stress." (PMID 26295265, 2015). "Several cell cycle checkpoint proteins have been studied as chemosensitizing targets for cancer therapy including ATR, CHK1 and WEE1." (PMID 26334102, 2015). "Collectively, these data demonstrate the synergistic anti-tumor effects of pharmacological WEE1 and CHK1 inhibition and highlight the potential of this unique combination in treating human cancer independently of chemotherapeutic drugs." (PMID 23148684, 2012).
cancer (continued). "This demonstration of DNA double strand breaks in the absence of a DNA damaging chemotherapeutic provides preclinical rationale for combining WEE1 and CHK1 inhibitors as a cancer treatment regimen." (PMID 23148684, 2012). "This review focuses on the molecular origins of RS in cancer, its impact on DNA damage responses and radiosensitivity, and current therapeutic efforts to exploit replication-stress vulnerabilities—particularly through inhibition of ATR, Chk1, Wee1, and PARP." (PMID 41614897, 2026). "Previous studies have demonstrated the inhibitory effects of compounds such as Alsterpaullone, Fostamatinib, Olomoucine, and Seliciclib on CDK1 activity, while agents like Adavosertib and Fostamatinib target WEE1, thereby indirectly modulating CDK1 activity and inhibiting cancer progression." (PMID 41009727, 2025). "Due to the important role of WEE1 in G1–S and G2–M cell-cycle checkpoints, high levels of baseline RS and DNA damage in KRAS-mutant cancer cells may confer sensitivity to WEE1 inhibition." (PMID 39807828, 2025). "Inhibition of WEE1 drives these cancer cells to enter unscheduled mitosis without adequate DNA repair, eventually triggering cell death as these levels of DNA damage become intolerable." (PMID 39807828, 2025). "Background/Objectives: This study explores the potential of LB-100 (a protein phosphatase 2A—PP2A inhibitor) combined with adavosertib (a WEE1 kinase inhibitor) and doxorubicin (DOX), to overcome multidrug resistance (MDR) in cancer cells and enhance treatment efficacy." (PMID 40006556, 2025). "Indeed, WEE1 has been shown to be a key dependency in KRAS-mutant cancers, and co-inhibition of KRAS with WEE1 and other cell-cycle and mitotic proteins has been identified as promising combination strategies through large-scale screening efforts." (PMID 39807828, 2025). "Moreover, genes related to cancer therapeutic targets, such as ABCG2, GSK3B, PTCH1, STAT3 and WEE1, were also upregulated." (PMID 39726234, 2025). "In addition to RNAi, small molecule inhibitors like Adavosertib, a WEE1 inhibitor, have been explored for their ability to inhibit cyclin E/CDK2 complexes, slowing down cell cycle progression in cancers with CCNE1 amplification." (PMID 39591374, 2024). "Wee1 is a downstream target for Chk1 kinase activity, and whilst similar to Chk1, this is considered an interesting cancer therapeutic target, although the development of more specific inhibitors of Wee1 has been lacking." (PMID 39272874, 2024). "WEE1 is well known for its role in regulating cell cycle checkpoint complexes composed of cyclin-dependent kinases (CDK) and cyclins, which controls the entry of cells into mitosis for DNA repair, a function that has implications in the cancer field." (PMID 39125637, 2024). "In addition to the receptors FGFR1, FGFR4 and ERBB4, the main effector AKT1 and its downstream effectors, MTOR, GSK3B, p21, WEE1, BAD and CREB5, which mediate cancer cell growth and progression, also exhibited marked changes in HPV-ind CCs." (PMID 38253702, 2024).
cancer (continued). "Additionally, PKMYT1 and WEE1 inhibition synthetically eradicates cancers with high levels of RS such as glioma and HGSOC, relatively sparing normal tissues or cancers with lower levels of RS." (PMID 38279263, 2024). "However, further experimental studies are needed to elucidate the specific roles of WEE1, PYHIN1, SEC61A2, and HAL in disease occurrence, progression, and response to treatment in both cancer and AMI." (PMID 37781709, 2023). "In summary, our findings suggest that WEE1, PYHIN1, SEC61A2, and HAL derived from monocytes may serve as a potential predictor for AMI and cancer prognosis." (PMID 37781709, 2023). "In our study, our findings suggest that WEE1, PYHIN1, SEC61A2, and HAL derived from monocytes may serve as a potential predictor for AMI and cancer prognosis." (PMID 37781709, 2023). "Particularly, compound 4 has demonstrated significant therapeutic potential against various cancer types, exhibiting inhibitory and anti-proliferation characteristics that are comparable to, if not better than, existing WEE1 inhibitors." (PMID 38143493, 2023). "Moreover, WEE1, a protein kinase overexpressed in ALL and involved in cell-cycle regulation, has been known to be a novel therapeutic target in many cancers." (PMID 37834095, 2023). "In fact, Wee1 and Myt1 have been found overexpressed in a variety of tumors, and a large-scale CRISPR screening revealed that both kinases are essentially required for cancer cell viability." (PMID 35563769, 2022). "WEE1 and PKMYT1 can act like oncogenes and are a major focus in anti-cancer drug development." (PMID 36276148, 2022). "Accordingly, targeting DDR damage proteins like Wee1 and modulating DRR signaling and the DSB repair pathway provided a fresh perspective into carcinogenesis and cancer treatment, notably in hematological malignancies where the dysfunctional DNA damage repair mechanism is highly involved." (PMID 36575478, 2022). "Until the present time, a plethora of different Wee1 targeting compounds have been preclinically screened and checked in different tumors, including CCA, with encouraging anti-cancer activity both as single agents and in combination with systemic or targeted therapeutics." (PMID 35563769, 2022). "Besides, applications of ATR/CHK1/WEE1 small-molecule inhibitors plus PARP inhibitors have been suggested, especially for cancer cells resistant to PARPi." (PMID 36253861, 2022). "Our findings substantially agree with the idea that Wee1 is rapidly recruited at DSBs in response to DNA damage via ATM-γH2AX-MDC1, driving Wee1 to recruit downstream HR repair proteins BRCA1 and RAD51 to DNA damage sites, as well as allowing cancer cells to escape damage and survive." (PMID 36575478, 2022). "Yet compared to Wee1, PKMYT1 is much less studied in the context of cancer biology." (PMID 35251998, 2022). "Cancer cells often show elevated replication stress due to, for example, oncogene expression or tumor hypoxia, which likely provides sensitivity to ATR or WEE1 inhibitors." (PMID 34359691, 2021). "Thus, using targeted agents for DDR pathways, including inhibitors of ATR/CHK1, PARP, ATM, cyclin-dependent kinase 4/6 (CDK4/6), DNA-PK, WEE1, and aurora kinase B (AURKB) opens new exciting avenues for clinical development of ICB for cancer treatment." (PMID 34930377, 2021). "Altogether, our results support that combining WEE1 and ATR inhibitors may be beneficial for cancer treatment in some cases, but also highlight that the effects vary between cancer cell lines." (PMID 34359691, 2021).
cancer (continued). "It is thus not surprising that some cancers are accompanied by WEE1 overexpression, which decreases their sensitivity to radiotherapy and chemotherapy." (PMID 34977872, 2021). "Overall, it has been shown that the rough tumor microenvironment of PDA cancer cells renders them chemoresistant, and in combination with HuR’s posttranscriptional regulation of specific target genes (COX-2, VEGF, c-Myc, WEE1 and PIM1), cell growth and survival are enhanced." (PMID 34572861, 2021). "Patients with higher Wee1 expression (> 50% of cancer cells) had a better overall survival (median OS: not reached for Wee1‐high group vs. 37.2 months for Wee1‐low patients, P = 0.038)." (PMID 33320980, 2021). "Based on promising early clinical trial results in other cancer types, more extensive testing using inhibitors of ATR (AZD6738) and WEE1 (AZD1775) was performed on 15 PDCLs defined as high and low replication stress based on the replication stress signature score." (PMID 33039466, 2021). "When over-expressed, PER1 was shown to set off apoptosis associated with DNA damage and altered expression of critical cell cycle controllers, such as WEE-1, Cyclin B1, and CDC2 in various human breast (MDAMB-231), colon (SW48), lung (NCI-H460), and endometrial (Ishikawa) cancer cell lines." (PMID 34440260, 2021). "Since BCL-2 and MCL-1 proteins may have overlapping anti-apoptotic functions with BCL-XL in cancer cells, we compared the impact of their mRNA expression levels, either alone or in combination with CDK1, CDK6 and WEE1, on the overall survival of TNBC patients." (PMID 34646365, 2021). "To assess whether Cyclin E1 overexpression affects the sensitivity of cancer cells to inhibitors of cell cycle checkpoint kinases, we induced Cyclin E1 overexpression and inhibited ATR and WEE1 kinases using VE-822 and MK-1775 respectively." (PMID 32964114, 2020). "Especially WEE1 (WEE1 G2 checkpoint kinase) is known to be an important cell cycle checkpoint kinase, but also ERBB3 (Erb-B2 receptor tyrosine kinase 3) is important in cancer development and has been identified as a potential target for treatment." (PMID 32252623, 2020). "Indeed, several DNA damaging agent promote the indirect activation of WEE1 and PKMYT1 kinases, as showed mostly by the activation of cell cycle checkpoints (S and G2/M checkpoints) in cancer cells." (PMID 32958072, 2020). "The biological role of WEE1 and PKMYT1 in cancer cells is not fully understood." (PMID 32958072, 2020). "To test whether high expression levels of Cyclin E1 influenced DNA replication kinetics and sensitivity of cancer cells to ATR and WEE1 inhibitor, we aimed to downregulate Cyclin E1 expression in TNBC cancer cells." (PMID 33028815, 2020). "To date, several Wee1 inhibitors have been investigated, some of which are concomitant CDK1 inhibitors, suggesting that Weel is an effective target for sensitizing various types of cancers to radiotherapy." (PMID 32355263, 2020). "Unlike silencing WEE1 in human cancer cell lines, where DDR depends on CDK2 but not CDK1, we demonstrate that DNA damage in Cdk1AF MEFs depends on CDK1 and not on CDK2." (PMID 30190546, 2019). "Impaired cell viability due to Wee1 inhibition has been shown for several cancer cell lines but not MPM." (PMID 30902996, 2019). "Although WEE1 inhibition effectively induces apoptosis in cancer cells, the effect of WEE1 inhibition on anti-apoptotic dependency is not well understood." (PMID 31703356, 2019).
cancer (continued). "Here, following evaluation of an underlying mechanism and in vivo validation of enhanced sensitivity to NK killing following WEE1 kinase inhibition with our murine model, we demonstrated that AZD1775 sensitized human cancer cells to both direct and ADCC-mediated killing." (PMID 29925431, 2018). "For one thing, AZD1775-reduced PLK1 may contribute to AZD1775-induced DNA damage and apoptosis still presented in WEE1 CRISPR-Cas9 knockout cancer cells, in line with reliance of AZD1775’s cytotoxicity on targeting PLK1 and WEE1 in our GC cells." (PMID 29954437, 2018). "WEE1 inhibitors might therefore be a therapeutic option for CLM and could be considered more broadly as anti-angiogenic agents in cancer treatment." (PMID 28178688, 2017). "In response to DNA damage or replication stress, KRAS-driven cancer cells activate G2 checkpoint kinases, such as ATR, Chk1, and Wee1, which might promote the survival of these cells." (PMID 28978051, 2017). "The miR-15 family has been verified to negatively regulate CHK1 and WEE1 at both the mRNA and protein levels, and reduction of CHK1 and WEE1 subsequently prolonged γ-H2AX expression after irradiation, which increased radiosensitivity of cancer cells." (PMID 27973455, 2016). "The sensitivity to the WEE1 inhibitor results through DNA replication stress because of RRM2 depletion, suggesting that other cancers exhibiting such replication stress may be targeted similarly." (PMID 26602815, 2015). "Because Wee1 is inhibited, cancer cells do not undergo cell cycle arrest, so mitosis continues despite radiation-induced injury to DNA." (PMID 17177986, 2006). "Hence, reducing MYC activity limits the cell’s ability to cope with replication stress, and when this is coupled with inhibition of key DNA repair pathways such as ATR/CHK1, WEE1, DNA-PKcs, or PARP, cancer cells can be pushed toward irreversible genomic instability." (PMID 41561634, 2025). "Subsequent inhibition of WEE1 G2 checkpoint kinase (WEE1) kinase results in synthetic lethality, highlighting how manipulating upstream or downstream pathways of CYP51A1 may promote selective cancer cell death." (PMID 40659633, 2025). "Moreover, inhibitors targeting different stages of the cell cycle, such as ATM inhibitors, ATR inhibitors, WEE1 inhibitors, and CHK1 inhibitors, have been developed in recent years, and their combination with PARP inhibitors has demonstrated enhanced anti-cancer efficacy." (PMID 40606759, 2025). "Although WEE1 inhibition has not been extensively tested in other cancers, its fundamental role suggests similar responses could occur." (PMID 39820427, 2025).